MIR3117 (microRNA 3117)
Synonyms: hsa-mir-3117; mir-3117
Gene: MicroRNA gene on chromosome 1 (66,628,440 to 66,628,517, forward strand). Ensembl gene ENSG00000264720.
Homologues: Orthologues: chimpanzee MIR3117 (100% identical).